BDNF (brain derived neurotrophic factor)
Diseases named in the same sentence as BDNF in open-access papers (continued):
Sharing a sentence is not in itself a finding about the gene and the disease.
psychiatric disorder (continued). "Although this neurotrophin has been considered for the treatment of neurological and psychiatric disorders, clinical trials with BDNF have been unsuccessful (Tejeda & Diaz‐Guerra, 2017)." (PMID 31273936, 2019). "Despite the central role of BDNF in psychiatric disorders development, little is known about the structural and functional effects of its mutations." (PMID 30998730, 2019). "These neurotrophins, particularly brain-derived neurotrophic factor (BDNF), appear to be involved in the pathophysiological basis of many neurodegenerative and psychiatric disorders." (PMID 31024364, 2019). "Thus, considering that these parameters are determinant for protein interactions and, consequently, protein function; the alterations observed during the MD analyses may be related to the functional impairment of BDNF upon V66M mutation, as well as its involvement in psychiatric disorders." (PMID 30998730, 2019). "The neurotrophin BDNF has emerged as a critical molecular player in central nervous system (CNS) development, psychiatric disorders, and AUDs13–15." (PMID 30728347, 2019). "In brief, BDNF has potential role in pathophysiology of many psychiatric diseases or serves as a therapeutic target for treatment of these diseases." (PMID 29795686, 2018). "For example, a high level of brain-derived neurotrophic factor (BDNF) in the PFC has been found to prevent or reverse stress-related mental illness by enhancing stress resilience." (PMID 29416077, 2018). "The role of the brain-derived neurotrophic factor (BDNF) in some psychiatric disorders, such as MDD and SZ, is well stablished." (PMID 29751665, 2018). "Meta-analyses and reviews of clinical studies based on the measurement of BDNF in whole blood, serum, or plasma have reported significantly lower BDNF levels at diagnosis in patients with mental illnesses." (PMID 29568518, 2018). "Brain-derived neurotrophic factor (BDNF) is under a pivotal role in the psychiatric disorders, including alcohol dependence." (PMID 29520063, 2018). "Research has evidenced the link of BDNF as a molecular factor involved in the pathophysiology of mental disorders." (PMID 29299044, 2017). "There is also an extensive literature about defective BDNF/TrkB signalling in cell and animal models of neurological and psychiatric disorders; therefore, we will prioritize here data obtained in preclinical models and human beings." (PMID 28134845, 2017). "Since its crucial role in brain development and brain plasticity, BDNF has been widely investigated also in several psychiatric diseases, including BPD." (PMID 28619017, 2017). "Both mature BDNF and proBDNF were proved to have important biological function in the pathology of psychiatric disorders such as MDD." (PMID 28241064, 2017). "miR-195-5p regulates serotonergic signaling and BDNF level—two biochemical pathways strongly involved in pathophysiology of mental illness." (PMID 27660265, 2017). "The reviewed data generally support the putative involvement of BDNF in the pathogenesis of stress-related mental illness." (PMID 28620285, 2017). "To demonstrate the utility of BECon, we assessed key candidate genes often investigated for changes in DNAm in relation to psychiatric disorders (BDNF, COMT, OXTR and DRD4)." (PMID 28763057, 2017). "BDNF is a molecular mediator of synaptic plasticity, hence, the BDNF signaling pathway is reduced in many neurodegenerative and psychiatric diseases." (PMID 28933745, 2017). "Previous work has revealed that targeting BDNF signalling by miRNAs has therapeutic potential in neurodegenerative and psychiatric diseases." (PMID 28838324, 2017). "Malfunction of BDNF/TrkB also plays a role in the pathophysiology of psychiatric disorders although the available evidence is still limited." (PMID 28134845, 2017). "There is growing evidence indicating that BDNF is related to many psychiatric disorders such as MDD in human studies." (PMID 28241064, 2017).
psychiatric disorder (continued). "The total measurements of serum tPA, PAI-1, BDNF, proBDNF, TrkB and p75NTR concentrations were suggested to be a promising assistance for diagnosing mental illness accurately in the early stage." (PMID 28761093, 2017). "Meta-analytical evidence suggests that brain-derived neurotrophic factor (BDNF) is altered in various psychiatric disorders." (PMID 27959329, 2016). "DNA methylation alterations of BDNF, in connection to various psychiatric disorders, have been extensively studied in last several years." (PMID 27267954, 2016). "Despite a relatively large number of studies, the use of the BDNF methylation level as a biomarker of psychiatric disorders still needs considerable further research to become reality." (PMID 27267954, 2016). "Brain-derived neurotrophic factor (BDNF), a protein important to nervous system function, has been implicated in psychiatric disorders and suicidal behaviour." (PMID 27121496, 2016). "So far only Keller’s study and our analysis indicate a partial correlation of the BDNF methylation level in the brain to the development of psychiatric disorders." (PMID 27267954, 2016). "In this network, BDNF and NGF are upstream of VGF and highly associated with psychiatric disorders and neurogenesis." (PMID 27877109, 2016). "Brain-derived neurotrophic factor (BDNF) plays an important role in nervous system development and function and it is well established that BDNF is involved in the pathogenesis of a wide range of psychiatric disorders." (PMID 27267954, 2016). "Using open access databases, we have analyzed the DNA methylation level of BDNF promoters in brain samples of individuals with psychiatric disorders." (PMID 27267954, 2016). "As a key regulator of synaptic development and plasticity, BDNF has been recognized to play a pivotal role in several neurodegenerative and psychiatric disorders." (PMID 27525025, 2016). "As briefly mentioned in the Introduction section, peripheral BDNF promoter has been increasingly used in the field of epigenetics of major psychiatric disorders." (PMID 26876488, 2016). "This is a significant question, since cognitive ability and synaptic plasticity are influenced by the levels of BDNF and BDNF signaling is reduced in many neurodegenerative and psychiatric diseases." (PMID 27253067, 2016). "In this review, we have summarized the information about individual CpG sites and CpG regions previously tested in BDNF promoters and shown to be connected to psychiatric disorders." (PMID 27267954, 2016). "As a precursor of BDNF, proBDNF can be useful to identify the mechanism of the neurodegeneration in the psychiatric diseases." (PMID 26405456, 2015). "Nevertheless, some meta-analysis of case-control studies examined changes in BDNF following pharmacologic treatment in psychiatric disorders." (PMID 26453695, 2015). "Due to its specific role during neurotransmission, the balance of BDNF has been reported to provoke neurological and psychiatric disorders, since the expression level of BDNF mRNA significantly decreases under stress induction." (PMID 24454754, 2014). "Abnormalities in BDNF and trkB−TK+ mRNA levels have been reported in various brain regions in those affected by psychiatric disorders and have been replicated in several cohorts." (PMID 24802307, 2014). "Replication of significant markers will serve us in establishing the most sensitive and reliable tools for future research into ‘synapse repair’ strategies in the prevention and treatment of neurodegenerative and psychiatric disorders utilizing BDNF." (PMID 24760076, 2014). "As a consequence, BDNF has become a key target in the pathology of several neurological and psychiatric diseases, and clinical studies have shown that BDNF protein expression is significantly decreased in both the serum and brain of depressed patients." (PMID 23805233, 2013).
psychiatric disorder (continued). "Further studies are necessary to define how the interaction between BDNF, metabolism and the epigenome are central for the effects of environmental factors on the etiology of many neurological and psychiatric disorders." (PMID 23483949, 2013). "Therapeutic modulation of BDNF level remains a promising treatment strategy for neurological and psychiatric disorders in which the level of BDNF is dysregulated." (PMID 23320097, 2013). "In addition, changes to the amount and chain length of PSA may influence psychiatric disorders through impaired binding to brain-derived neurotrophic factor and dopamine, which are linked to schizophrenia and other psychiatric disorders, such as depression and bipolar disorder." (PMID 23922842, 2013). "The potential role of BDNF in psychiatric disorders has been extensively studied at the gene and protein levels, though no clear conclusion has been reached." (PMID 22539971, 2012). "REST has been shown to regulate the neurotrophic factor BDNF (brain-derived neurotrophic factor) with implications for psychiatric disease." (PMID 18959489, 2008). "Also, BDNF which can regulate activity-dependent synaptic plasticity and psychiatric disorders was assessed." (PMID 41484454, 2026). "Cluster #11 examines how ketone bodies, particularly β-hydroxybutyric acid, enhance BDNF expression and neuroprotection, implying that combining nutritional strategies with exercise could effectively tackle psychiatric disorders." (PMID 40964429, 2025). "The demonstrated efficacy of HIFN in preserving vision and preventing progressive damage following traumatic injury suggests its potential utility in addressing a wide range of neurological and psychiatric disorders characterized by compromised BDNF/TrkB signaling." (PMID 40027732, 2025). "However, in individuals with psychiatric disorders, a reduction in BDNF levels is observed, possibly due to changes in its genetic expression and the occurrence of polymorphisms in coding regions." (PMID 40342368, 2025). "Similarly, our result of increased liver BDNF levels in KIV mice is also consistent with past research suggesting that patients with psychiatric disorders typically show lower BDNF levels in the brain but higher levels in liver compared to normal controls." (PMID 40316902, 2025). "The BDNF signaling has shown relevance to neurodegenerative diseases and psychiatric disorders where solutions may be tailored to meet genetic and molecular specificities across individuals." (PMID 40362507, 2025). "The mechanism of action of cerebrolysin (which could potentially be the focus of interest if we take into account psychiatric diseases) involves the stimulation of BDNF synthesis." (PMID 40722733, 2025). "BDNF plays a crucial role in various neurological and psychiatric disorders." (PMID 40508005, 2025). "Finally, postmortem studies have reported lower BDNF protein levels in the hippocampus and prefrontal cortex of individuals with psychiatric disorders who have died by suicide, compared to non‐psychiatric controls." (PMID 40103195, 2025). "TrkB/BDNF signaling has important roles in a wide range of neurodegenerative disorders ranging from Alzheimer’s and Parkinson’s diseases, amyotrophic lateral sclerosis, to optic neuropathies, as well as psychiatric disorders such as depression." (PMID 40027732, 2025). "These declines in BDNF may occur prior to clinical manifestations of neurodegenerative and psychiatric disease; therefore, it offers a potentially useful biomarker for those in their preclinical phase." (PMID 40362507, 2025). "It would be interesting to determine whether disruption of DLS signaling in psychiatric disorders resulting in maladaptive habitual and compulsive behaviors can be restored by activation of BDNF signaling in the DLS." (PMID 39868120, 2025).
psychiatric disorder (continued). "This review will describe how these technologies may overcome traditional obstacles to provide scalable and specific ways to improve BDNF activity in many neurological and psychiatric disorders." (PMID 40362507, 2025). "Given the pivotal role of miRNA in regulating gene expression through epigenetic mechanisms across various psychiatric disorders, there’s a pressing need to delve deeper into the downstream targets of miR-10a-5p, particularly brain-derived neurotrophic factor (BDNF), within the context of PPD." (PMID 39588356, 2024). "Prenatal stress has been shown to reduce BDNF expression in several stress-related brain areas at weaning and adulthood in rats, altering then neuronal plasticity and possibly leading to increased vulnerability for psychiatric disorder development." (PMID 40656087, 2024). "This study underscores the intricate role of BDNF’s various forms in the development of the nervous system and their potential long-term impacts on behavior, offering new insights into the neurobiological underpinnings of psychiatric disorders." (PMID 39619203, 2024). "Alterations in BDNF pathways have been described in several psychiatric disorders." (PMID 39203753, 2024). "Reduced BDNF levels in the central and peripheral systems are closely related to various neurological diseases, including neuropathic pain, inflammatory pain, and mental illness." (PMID 39648800, 2024). "In conclusion, although research into the role of BDNF as a biomarker for psychiatric disorders and metabolic disorders has been fruitful, the current limitations make it difficult to definitively assert its utility as a diagnostic or prognostic biomarker for AN." (PMID 39203753, 2024). "In recent years, different research groups have explored BDNF’s involvement in stress-related mental illnesses, particularly affective disorders, although the mechanisms responsible for these pathological states remain unclear." (PMID 38541632, 2024). "For these reasons, BDNF may be demarcated as a potent biomarker involved in the pathology of psychiatric disorders such as schizophrenia and OCD." (PMID 38125619, 2024). "The relationship between body weight and psychiatric disorders is intricate, with current research efforts aimed at deciphering these associations to enhance treatment and preventative measures for those impacted by psychiatric disorders, modulating BDNF's influence on neuroplasticity and cognition." (PMID 38988887, 2024). "Currently, most studies have suggested that BDNF may be a major factor in the development of psychiatric disorders." (PMID 38988887, 2024). "This epigenetic modification appears to persist long after the initial stressor, suggesting that BDNF gene silencing through methylation could contribute to long-term vulnerability to psychiatric disorders." (PMID 39595869, 2024). "The findings of this research have significant clinical implications, particularly for neurological and psychiatric disorders, which could worsen the already low levels of BDNF and further impair neuroplasticity and cognitive function." (PMID 39568824, 2024). "Our cohort was a follow-up study of participants who all had psychiatric disorders at baseline and the high levels of BDNF may have been found among those with ongoing symptoms since baseline, but this was not explored further." (PMID 38773198, 2024). "In summary, the BDNF‐mediated TrkB signaling pathway controls various neuronal functions and is involved in multiple molecular mechanisms that counteract various pathophysiological processes crucial to neurological and psychiatric disorders." (PMID 39648800, 2024). "The Trp to Kyn pathway could thus represent a potential mechanism linking the eCB and BDNF systems, providing insight into their involvement in the onset of psychiatric disorders triggered by stress." (PMID 38273283, 2024).
psychiatric disorder (continued). "It is important to note that while BDNF has shown associations with various psychiatric disorders, it is not a definitive diagnostic marker on its own." (PMID 37626739, 2023). "BDNF has also similar effects in other psychiatric disorders." (PMID 38066466, 2023). "Brain-derived neurotrophic factor (BDNF) played a vital role in neuronal growth, differentiation, survival, and synaptic plasticity, which was associated with the pathogenesis of various psychiatric diseases." (PMID 37533888, 2023). "Finally, the present results also highlight the potential of BDNF as a therapeutic target for specific neurological and psychiatric diseases." (PMID 37569576, 2023). "It is still unknown if BDNF should be considered as a trans-nosographic marker for more psychiatric disorders, or if it is pathognomonic of a specific condition, such as BD." (PMID 37626577, 2023). "Collectively, these findings suggest that the coordinated actions of BDNF and glucocorticoids promote neuronal plasticity and that disruption in either pathway may lead to stress-induced psychiatric disorders." (PMID 37298449, 2023). "Indeed, as recalled above, in patients with psychiatric disorders, markedly reduced BDNF levels correlate with low superoxide dismutase and glutathione peroxidase, with a substantial rise in malondialdehyde (MDA) and end product of lipid peroxidation." (PMID 36214902, 2023). "Homeostatic plasticity of BDNF in the hippocampus may be involved in the therapeutic mechanisms of psychiatric disorders." (PMID 37780709, 2023). "Previous works have found that BDNF is involved in several neurological or psychiatric diseases." (PMID 37626577, 2023). "Previous studies have revealed lower serum BDNF levels in patients with mental illnesses." (PMID 35114967, 2022). "In most studies serum BDNF correlates negatively with psychiatric disorders and disease severity." (PMID 35114967, 2022). "Patients suffering from psychiatric disorders exhibit lower levels of BDNF than healthy controls." (PMID 36672535, 2022). "There are also prominent anatomical differences in BDNF pro-peptide expression throughout the body which may determine the role it plays in neurodegenerative or psychiatric disease." (PMID 35887357, 2022). "Overall, BDNF levels are negatively correlated in neurodegenerative and psychiatric disorders." (PMID 35887357, 2022). "In addition, reduced BDNF levels were detected in the parietal cortex, mPFC, and hippocampus of the postmortem brains of patients with psychiatric disorders, including MDD." (PMID 36316319, 2022). "Accordingly, BDNF is emerging as a cornerstone in the treatment of psychiatric disorders, and MgPid might contribute to alleviating the symptoms by increasing BDNF levels in the brain." (PMID 35563524, 2022). "Moreover, recent evidence shows that BDNF, similar to oxytocin, regulates social and maternal behavior, eating behavior as well as obesity, impacting other psychiatric disorders such as autism and schizophrenia and, as mentioned, mood and anxiety disorder." (PMID 35888641, 2022). "If specific contextual aspects of BDNF and its isoforms can be established, then these mechanisms can be manipulated in a beneficial way to successfully treat patients affected with a range of neurodegenerative and psychiatric disorders." (PMID 35887357, 2022). "BDNF deficiency due to epigenetic alterations has been linked to a plethora of psychiatric diseases, suggesting that the lack of BDNF is a central biomarker for such disorders." (PMID 35937892, 2022). "Our work suggests the physiological (here, gene expression) result of genetic BDNF variation that may contribute to specific psychiatric disorders in symptomatology and behavioral phenotypes." (PMID 33757426, 2021). "This may be a protective mechanism since the reverse profile i.e., higher liver BDNF and lower brain BDNF is found in psychiatric disorders." (PMID 34248683, 2021).